DNAH14 (dynein axonemal heavy chain 14)
Description:
Force generating protein of respiratory cilia. Produces force towards the minus ends of microtubules. Dynein has ATPase activity; the force-producing power stroke is thought to occur on release of ADP. Involved in sperm motility; implicated in sperm flagellar assembly (By similarity).
Synonyms: C1orf67; Dnahc14; HL-18; HL18; DKFZp781B1548; MGC27277
Tractability: PROTAC: ubiquitination databases record sites on it.
Gene: Protein-coding gene on chromosome 1 (224,896,262 to 225,399,292, forward strand). Ensembl gene ENSG00000185842.
Subcellular location: Cytoplasm, cytoskeleton, cilium axoneme
Subcellular location (Human Protein Atlas): Basal body; Centrosome; Golgi apparatus
Gene Ontology:
Molecular function: dynein intermediate chain binding; dynein light intermediate chain binding; minus-end-directed microtubule motor activity; ATP binding
Biological process: cilium movement involved in cell motility; microtubule-based movement
Cellular component: 9+2 motile cilium; dynein complex; axoneme; cilium
Genetic constraint (gnomAD): Loss-of-function variants: 344 observed, 388.22 expected, observed/expected ratio (o/e) 0.89, 90% interval 0.81 to 0.97. The upper end of that interval is the gene's LOEUF score, 0.97, which puts it in group 4 of 6, group 1 being the genes least tolerant of losing a copy. Missense variants: 4,000 observed, 4,482.1 expected, observed/expected ratio (o/e) 0.89, 90% interval 0.87 to 0.92. Synonymous variants: 1,331 observed, 1,539.9 expected, observed/expected ratio (o/e) 0.86, 90% interval 0.82 to 0.9.
Gene-disease validity (ClinGen):
ClinGen rates the evidence that DNAH14 causes each of these diseases.
primary ciliary dyskinesia (autosomal recessive): Disputed. A rare, genetically heterogeneous, primarily respiratory disorder characterized by chronic upper and lower respiratory tract disease.
Homologues: Orthologues: chimpanzee DNAH14 (94% identical), dog DNAH14 (75% identical), pig DNAH14 (67% identical), guinea pig DNAH14 (65% identical), rat Dnah14 (64% identical), mouse Dnah14 (63% identical). Paralogues in human: DNAH6 (32% identical), DNAH2 (26% identical), DNAH7 (26% identical), DNAH1 (26% identical), DNAH3 (26% identical), DNAH12 (25% identical), DNAH10 (25% identical), DNAH11 (24% identical), DNAH9 (23% identical), DNAH5 (23% identical), DNAH17 (23% identical), DNAH8 (22% identical), and 3 more.
Diseases named in the same sentence as DNAH14 in open-access papers:
DNAH14 is named in the same sentence as 33 diseases in open-access papers, as found by Europe PMC text mining. Sharing a sentence is not in itself a finding about the gene and the disease. The quoted sentences say what the papers report.
ciliopathies (2 papers, 2026). "Recent studies suggest a broad spectrum of phenotypes associated with DNAH14 mutations, ranging from neurodevelopmental disorders to ciliopathies." (PMID 41596228, 2026). "Third, a c.2060A > T (p.Asp687Val) variant was found in DNAH14, a gene that regulates ciliary movement, with mutations associated with ciliopathies that may overlap with lymphatic defects." (PMID 41530801, 2026).
cystic fibrosis (2 papers, 2021 to 2024). Autosomal recessive disorder caused by pathogenic variants in the CFTR gene (cystic fibrosis transmembrane conductance regulator), which encodes a chloride and bicarbonate channel expressed in epithelial cells, and follow the diagnosis criteria. "Variants in genes underlying the development or function of cilia, such as DNAH14 and DNAAF3, were associated with poor lung function in cystic fibrosis, whereas variants in DNAH6 were associated with preserved lung function in cystic fibrosis." (PMID 39337527, 2024). "Lastly a heterozygous variant in DNAH14 (MIM 603341; 1q42.12), a candidate gene for primary ciliary dyskinesia and lung function in cystic fibrosis, may play a role in ID6′s susceptibility to airway infections." (PMID 33924653, 2021).
Hydrocephalus (2 papers, 2021 to 2026). Hydrocephalus is an active distension of the ventricular system of the brain resulting from inadequate passage of CSF from its point of production within the cerebral ventricles to its point of absorption into the systemic circulation. "Since DNAH14 encodes an axonemal dynein in motile cilia, the authors suggested that its deletion may disrupt cilia function during hydrocephalus pathogenesis." (PMID 41596228, 2026). "Since DNAH14 encodes axonemal dynein in motile cilia, the authors suggested that DNAH14 deletion may affect the physiological function of cilia during hydrocephalus pathogenesis." (PMID 33999288, 2021).
male infertility (2 papers, 2022 to 2024). The inability of the male to effect fertilization of an ovum after a specified period of unprotected intercourse. "Currently, 13 members of the DNAH gene family have been reported, including DNAH1 to DNAH3, DNAH5 to DNAH12, DNAH14, and DNAH17, among which 11 genes (DNAH1, DNAH2, DNAH5 to DNAH12, and DNAH17) are associated with male infertility." (PMID 38312775, 2024). "In humans, there are 13 dynein axonemal heavy chain (DNAH) proteins (DNAH1–3, DNAH5–12, DNAH14, and DNAH17) and mutations in many of these genes have been associated with male infertility." (PMID 36140773, 2022). "Eleven of them have been found to be involved in male infertility, whereas the role of DNAH3 and DNAH14 in male infertility has not been clarified." (PMID 38312775, 2024).
primary ciliary dyskinesia (2 papers, 2021 to 2026). "Several axonemal dynein genes have been implicated in the etiology of primary ciliary dyskinesia; however, DNAH14 has not yet been associated with a documented phenotype in the OMIM database." (PMID 41596228, 2026).
asthma (1 paper, 2024). "Additional genetic factors, such as genetic variations in some PCD-causing genes (DNAH14, DNAAF3, DNAH6, DNAH5, KIFC2, KIF3A), are associated with the increased risk of asthma development." (PMID 39337527, 2024).
Ataxia (1 paper, 2026). Ataxia refers to impaired coordination of voluntary muscle movement. "In this study, we present two siblings with neurodevelopmental delay and ataxia, carrying a homozygous pathogenic variant in DNAH14 and pathogenic GAA repeat expansions in the FXN gene in both siblings, confirming a diagnosis of Friedreich’s ataxia (FRDA)." (PMID 41596228, 2026). "Our findings expand the phenotypic spectrum of DNAH14-related disorders and highlight the importance of considering multilocus pathogenic variants in patients with complex or atypical ataxia presentations." (PMID 41596228, 2026). "Reports of DNAH14-related cases in the literature, describing patients with microcephaly, hypotonia, seizures, ID, and ataxia, further support this hypothesis." (PMID 41596228, 2026). "The coexistence of FRDA expansions and a truncating DNAH14 variant suggests a potential dual genetic contribution to the observed phenotype, in which FRDA-associated pathology likely underlies the ataxia, while DNAH14 disruption may contribute to additional neurodevelopmental features." (PMID 41596228, 2026). "This dual molecular finding provides a more comprehensive explanation for their phenotype: the ataxia and cerebellar features align with FRDA pathology, while the coexisting intellectual disability is atypical for FRDA and may reflect the additive effect of the DNAH14 truncating variant." (PMID 41596228, 2026).
bronchiectasis (1 paper, 2026). Segmental, irreversible dilation of the bronchial tree resulting in the accumulation of secretions which leads to obstruction. "They identified compound heterozygous DNAH14 variants in a 5-year-old male patient presenting with recurrent wet cough, bronchiectasis, chronic sinusitis, and reduced nasal nitric oxide (nNO) levels (63 nL/min)." (PMID 41596228, 2026).
cerebral arteriovenous malformations (1 paper, 2026). "Subsequent studies have associated DNAH14 with diverse phenotypes, including panventriculomegaly, cerebral arteriovenous malformations, PCD, ID, and neurodevelopmental delay with seizures." (PMID 41596228, 2026).
depressive episodes (1 paper, 2024). "The most significant hits were for the number of manic episodes, with SLC13A3 as top gene in BP-I and TNRC6C in BP-II, followed by the number of depressive episodes, with MTSS1 as top gene in BP-I and DNAH14 in BP-II." (PMID 38865039, 2024).
developmental delay (1 paper, 2026). "Recent studies have linked DNAH14 variants to a spectrum of neurodevelopmental disorders, including global developmental delay, seizures, microcephaly, and hypotonia." (PMID 41596228, 2026). "They suggested DNAH14 as a candidate gene for ID in a male patient with global developmental delay, hypotonia, and neuroregression, despite a normal cranial MRI and metabolic screening." (PMID 41596228, 2026).
Friedreich ataxia (1 paper, 2026). An inherited condition that affects the nervous system and causes movement problems. "While the presence of GAA expansions in FXN establishes Friedreich’s ataxia as a major contributor to the ataxic presentation, the coexistence of a homozygous truncating DNAH14 variant likely modifies the clinical phenotype." (PMID 41596228, 2026).
gastric cancer (1 paper, 2013). A primary or metastatic malignant neoplasm involving the stomach. "DNAH14 has also been found to be differentially regulated in response to taxane therapy in gastric cancers and doxorubicin therapy in endometrial cells." (PMID 23555554, 2013).
Intellectual disability (1 paper, 2026). "The intellectual disability observed in our patients, therefore, exceeds the expected cognitive profile of FRDA and suggests additional contribution from DNAH14 disruption." (PMID 41596228, 2026).
Neurodevelopmental delay (1 paper, 2026). "Despite these findings, the DNAH14 gene has not yet been linked to a specific phenotype in the Online Mendelian Inheritance in Man (OMIM) database, and no large-scale studies have systematically evaluated its relationship with neurodevelopmental delay." (PMID 41596228, 2026).
pneumonia (1 paper, 2026). An acute, acute and chronic, or chronic inflammation focally or diffusely affecting the lung parenchyma, caused by an infection in one or both of the lungs (by bacteria, viruses, fungi, or mycoplasma.). "Notably, two of these three patients had a history of pneumonia, leading Li and colleagues to suggest that DNAH14 variants may increase susceptibility to respiratory infections." (PMID 41596228, 2026).
Primary microcephaly (1 paper, 2024). Head circumference below 2 standard deviations below the mean for age and gender at birth. "Additionally, mutations in the genes Dnah2 and Dnah14, which contribute to motile cilia structure, have been associated with primary microcephaly, neurodevelopmental disorders, and other conditions such as seizures." (PMID 39594631, 2024).
rectal cancer (1 paper, 2022). A primary or metastatic malignant neoplasm that affects the rectum. "Genetic variation in DNAH14 rs3105571 has been described and is significantly associated with pathologic complete response to neoadjuvant chemoradiotherapy in locally advanced rectal cancer." (PMID 34996478, 2022).
spinocerebellar ataxia type 11 (1 paper, 2025). Spinocerebellar ataxia type 11 (SCA11) is a subtype of autosomal dominant cerebellar ataxia type III (ADCA type III) characterized by the early-onset of cerebellar signs, eye movement abnormalities and pyramidal signs. "Thus, dysfunctional TTBK2 causes spinocerebellar ataxia type 11, and mutations of DNAH14 cause neurodevelopmental deficits." (PMID 40019676, 2025).
cancer (4 papers, 2018 to 2022). A tumor composed of atypical neoplastic, often pleomorphic cells that invade other tissues. "Our machine learning-based analysis provides insights into the aberrant landscape and biogenesis of circRNAs in cancer and highlights cancer mutation-related and DNAH14-derived circRNA, chr1_224952669_224968874_+, as a potential cancer biomarker." (PMID 34604037, 2021). "Our results highlight the cancer mutation-related and DNAH14-derived circRNA, chr1_224952669_224968874_+, as a potential cancer biomarker." (PMID 34604037, 2021). "Specifically, the circRNA chr1_224952669_224968874_+ related to a splice acceptor variant of DNAH14 (chr1:224952669:G>A) was a pan-cancer tissue-enriched circRNA significantly elevated in plasma exosomes from CRC and HCC patients." (PMID 34604037, 2021). "The pan-cancer tissue-enriched chr1_224952669_224968874_+ and chr1_224952669_224974153_+ were related to the splice acceptor variant of DNAH14 (chr1:224952669:G>A)." (PMID 34604037, 2021). "DNAH14 encodes a microtubule-associated motor protein that participates in maintaining the integrity of centrosomes, and it is often numerically, positionally, or structurally dysregulated in cancer." (PMID 34604037, 2021). "Here, we hypothesized that the splice acceptor variant chr1:224952669:G>A (DNAH14) is relatively frequent in cancer tissues and cancer-specific circRNAs." (PMID 34604037, 2021). "We identified dynein axonemal heavy chain 14 (DNAH14), the top back-spliced gene exclusive to pan-cancer tissues, as the host gene of three pan-cancer tissue-enriched circRNAs." (PMID 34604037, 2021). "chr1_224952669_224968874_+ was 2- to 4-fold elevated in pan-cancer tissues, while the expression level of DNAH14 was similar in pan-cancer and pan-normal tissues." (PMID 34604037, 2021). "Dynein axonemal heavy chain 14 (DNAH14) was the third most actively back-spliced gene exclusive in pan-cancer tissues." (PMID 34604037, 2021). "We highlighted the potential role of DNAH14 as an important host gene of circRNAs in cancer." (PMID 34604037, 2021). "Interestingly, a recent study has identified DNAH14 as one of the 21 passenger genes in EC suggesting that DNAH14 aberration could interfere with cancer-related pathways." (PMID 29464034, 2018). "Then, through the signaling transmission of cascade proteins DNAH14 and CPSF4, it could enter the nucleus to downregulate TF MED17, resulting in an androgen-dependent reduction of cancer cells." (PMID 35164166, 2022). "Although DNAH14 was not upregulated in cancer tissues, chr1_224952669_224968874_+ was elevated and increasingly transcription-driven." (PMID 34604037, 2021). "DNAH14 was the third-highest back-spliced host gene in pan-cancer tissues but was not among the top back-spliced host genes in the pan-normal tissues, although the overlap between the top back-spliced genes in pan-cancer and pan-normal tissues was prominent." (PMID 34604037, 2021). "Interestingly, chr1_224952669_224968874_+ levels were positively correlated with DNAH14 expression in the pan-cancer tissues but not in the pan-normal tissues." (PMID 34604037, 2021).
neurodevelopmental disorder (4 papers, 2024 to 2026). A behavioral and cognitive disorder with onset during the developmental period that involves impaired or aberrant development of intellectual, motor, or social functions. "Across all reported cases, biallelic DNAH14 variants give rise to a broad clinical spectrum ranging from PCD to neurodevelopmental disorders." (PMID 41596228, 2026). "Although DNAH14 has recently been implicated in neurodevelopmental disorders, available data is limited." (PMID 41002930, 2025). "Recently, DNAH14 and SYT1 variants have been implicated in neurodevelopmental disorders." (PMID 38886689, 2024).
neurological disease (1 paper, 2026). "Finally, integration of iPSC-derived models with transcriptomic, proteomic, and live-cell imaging approaches provides a comprehensive framework to identify molecular pathways underlying DNAH14-associated pathogenesis and to link early cellular dysfunction with progressive neurological disease." (PMID 41596228, 2026).
vascular disorder (1 paper, 2026). A general term used to describe any disease affecting blood vessels]. "Although there was no direct evidence linking DNAH14 to angiogenesis or other vascular disorders, their in silico analyses and segregation studies suggested that DNAH14 could be involved in BAVM pathogenesis." (PMID 41596228, 2026).
DNAH14 also shares sentences with these, for which no sentence is quoted: tumor (3 papers); biliary tract cancer (1); breast carcinoma (1); chronic sinusitis (1); infection (1); manic episodes (1); melanoma (1); microcephaly (1); ovarian carcinoma (1); respiratory infections (1).